FGF21 (fibroblast growth factor 21)
Diseases named in the same sentence as FGF21 in open-access papers (continued):
Sharing a sentence is not in itself a finding about the gene and the disease.
Obesity (continued). "It is hypothesized that individuals with obesity may be resistant to FGF21, whereby circulating levels are elevated but target tissues do not respond to the effects of FGF21." (PMID 32043413, 2020). "The discovery of endocrine fibroblast growth factors (FGF), including FGF-21 and FGF-19, has uncovered new mechanisms that regulate metabolism and lipid homeostasis, and has provided potential therapeutic targets for type 2 diabetes, obesity, and hepatic steatosis." (PMID 32069846, 2020). "Most of the myokines measured were regulated by acute exercise (FGF21, IL-6, IL-8, IL-15, and IL-18), and some were released at different levels in plasma over the 24 h in the group of women with obesity in comparison to the non-obese group (SPARC, IL-8, and IL-13)." (PMID 32132925, 2020). "The effect of fasting and ketogenic diets to increase FGF21 is not nearly as robust in humans as initially observed in mice, FGF21 is also increased in settings of obesity, and more recent work has led to the suggestion that FGF21 is more appropriately a signal of metabolic or cellular stress." (PMID 32047920, 2020). "In this study, we examined whether absence of FGF21 induces an obesity-induced atrophic response in skeletal muscle." (PMID 31312114, 2019). "Interestingly, we observed similar patterns of expression of genes encoding secreted factors in aged and obese adipose tissues, suggesting that PMATs act as a common accelerator of obesity- and aging-related muscle atrophy via those secreted proteins, among them, PAI-1, Leptin, and Fgf21." (PMID 31442231, 2019). "An animal study revealed that FGF21 specifically upregulates the glucose transporter 1 (GLUT1) with greater expression of GLUT1 mRNA at the adipocyte cellular membrane and then induces noninsulin-dependent glucose uptake in the insulin resistance model and obesity (ob/ob mice)." (PMID 31582974, 2019). "In addition to its function as a stress response hormone, the metabolic benefits of the pharmacological use of FGF21 have been well studied in rodents, nonhuman primates and humans, where it dramatically alleviated obesity and fatty liver disease." (PMID 31511499, 2019). "Altogether, let us hypothesize that FGF21 can be a target to treat obesity and several metabolic disorders, but perhaps not in the way that was previously proposed." (PMID 31546675, 2019). "FGF21 has been shown to have central effects, however whether or not central FGF21 co-receptor expression and signaling are altered during obesity remains unreported." (PMID 29983922, 2018). "Remarkably, VCE-004.8 increased the FGF21 mRNA expression in white and brown adipose, as well as in a BAT cell line, qualifying cannabinoaminoquinones as a class of novel therapeutic candidates for the management of obesity and its common metabolic co-morbidities." (PMID 30382123, 2018). "We demonstrate that SAT but not VAT is the major target of FGF21 in diet-induced obesity." (PMID 29348470, 2018). "Potentially, FGF21 sensitivity during obesity may be akin to insulin resistance whereby the biological effect of endogenous FGF21 is lacking yet pharmacological dosing elicits an effect." (PMID 29983922, 2018). "However, the pathophysiological role of elevated circulating FGF21 in obesity has never been explored." (PMID 29348470, 2018). "Since obesity has been identified as a state of FGF-21 resistance, it is logical to speculate that the higher levels of circulating FGF-21 are partly driven by high adiposity that accompanies overweight and/or obesity." (PMID 30298107, 2018). "However, based on dose response studies, these investigators concluded that circulating FGF21 is increased during obesity to maintain insulin sensitivity, and not due to “FGF21 resistance”5." (PMID 29983922, 2018).
Obesity (continued). "In the present study, we showed that FGF21 promoted M2 macrophage polarization and M2-related anti-inflammatory cytokine such as IL10 in subcutaneous fat, which may act as a compensatory response to maintain glucose homeostasis in diet-induced obesity." (PMID 29348470, 2018). "Moreover, improving hepatic insulin sensitivity and glucose homeostasis in the background of HFD-induced obesity did not decrease FGF21 levels in mice lacking hepatic PTP1B." (PMID 28256636, 2017). "Serum FGF21 levels are elevated in patients with obesity, type 2 diabetes, and nonalcoholic fatty liver disease (NAFLD) and could be considered as a biomarker of obesity-related metabolic diseases." (PMID 27190511, 2016). "Moreover, the in vivo half-life of intact native FGF21 is less than 2 hr across multiple species and therefore not ideal for development as a therapeutic for chronic metabolic diseases, such as T2D and obesity." (PMID 25790234, 2015). "To interrogate FGF21 pharmacology in a different species and confirm dependence on the leptin pathway on metabolic endpoints such as BW, glycemic control, we used Zucker fatty rats Strain 185 Crl:ZUC-Leprfa27 which lack the leptin receptor and develop obesity and hyperphagia." (PMID 26153793, 2015). "Given known effects of FGF21 in inducing brown adipogenesis and increasing REE, these changes likely represent an adaptive response to decrease brown adipogenesis and conserve energy in anorexia nervosa, and to increase brown adipogenesis and expend energy in obesity." (PMID 24926783, 2014). "The precise mechanism by which BM extract improves glucose metabolism is largely unknown, and the effects of BM extracts on FGF21 signaling in obesity and metabolic syndrome have not been studied." (PMID 24189525, 2013). "Fibroblast growth factor 21 (FGF21), whose expression is induced by peroxisome proliferator-activated receptor α (PPARα), has been recently identified as a novel metabolic regulator which plays a crucial role in glucose homeostasis, lipid metabolism, insulin sensitivity and obesity." (PMID 22394566, 2012). "Pharmacologically, FGF-21 induced glucose uptake through the induction of glucose transporter-1 (GLUT1) in adipocytes, and in vivo treatment with FGF-21 resulted in amelioration of glucose and lipid metabolism in both murine and nonhuman primate models of diabetes or obesity." (PMID 22046277, 2011). "Taken together, these findings demonstrate an important role of FGF-21 as a hepatic hormone in the regulation of lipid metabolism and also suggest that FGF-21 exhibits the therapeutic characteristics necessary for an effective treatment of obesity and fatty liver disease." (PMID 21206918, 2010). "Furthermore, since FGF21 is produced by hepatocytes, it is reasonable to assume that liver disease could affect its expression, with elevated FGF21 levels observed in MASH patients with obesity." (PMID 39409124, 2024). "Besides its metabolic attributes, FGF21 also seems to have an anti-inflammatory effect, which has been observed in patients with type 2 diabetes mellitus (T2DM) and diabetic peripheral neuropathy, and it seems to ameliorate obesity-related hypothalamic inflammation." (PMID 39452947, 2024). "Specifically, a significant relationship of FGF-21 level with increased odds of diabetes was detected in women, younger, and older subjects, subjects without hypertension, subjects without overweight and obesity, central obesity subjects and nondyslipidemia subjects (all P < 0.05)." (PMID 37658393, 2023). "Extra-cerebral effects of temperature or FGF21 in the context of obesity could also induce RBM3 release from other organs, and would be the more biologically plausible explanation of the increase in RBM3 in adult patients, thus providing new insight into the obesity paradox." (PMID 35207221, 2022). "Thus, the physiological role for obesity-induced FGF21 levels, if any, is not clear." (PMID 36034414, 2022).
Obesity (continued). "In addition, possible mechanisms related to epigenetic factors may contribute, especially in respect of FGF21 resistance in obesity, however our data do not support this hypothesis." (PMID 34762789, 2021). "However, it was unknown whether FGF15/19 could directly reduce hepatic lipid accumulation, especially when FGF21 was not function well, i.e., FGF21 resistance in obesity." (PMID 34326695, 2021). "Thus, much like the increased FGF21 levels observed in obesity, it is not yet clear whether increased cardiac FGF21 reflects a compensatory response to combat FGF21 resistance, or whether it could be detrimental when expressed from the heart." (PMID 35046901, 2021). "However, these beneficial effects on obesity, T2DM, and fatty liver disease seem to contrast with the high levels of FGF21 identified in these disorders, being currently difficult to specify whether this reflects a resistance to FGF21 or it is a compensatory reaction to basal metabolic stress." (PMID 35111794, 2021). "However,the pharmacological effects of FGF21 have not been studiedin melanocortin obesity models." (PMID 33659800, 2020). "We observed no significant increase in plasma FGF21 after the cycling bout in either groups, which confirms the findings of others regarding changes in plasma or serum FGF21 after exercise in patients with obesity, but contradicts the results obtained in healthy participants." (PMID 32132925, 2020). "Moreover, pharmacological administration of recombinant FGF21 reduced serum triglyceride (TG) and low-density lipoprotein cholesterol (LDL) while increased high-density lipoprotein cholesterol (HDL) levels, and it reversed steatosis in mouse models of obesity and diabetes." (PMID 33071964, 2020). "FGF21 influenceon FI in female rodent was not studied, but in males, FGF21was shown previously to increase FI in rats, mice with diet-induced obesity,and to increase protein intake while reducing carbohydrateintake in normal mice, and the later effect was mediated viaCNS." (PMID 33659800, 2020). "Thus, increases in circulating FGF21 levels do not result from obesity, and chronic increases in plasma FGF21 levels may precede diet-induced metabolic disturbances." (PMID 32978487, 2020). "Therefore, we suggest that CO acts as a potent mediator of metabolic homeostasis by increasing endogenous FGF21 expression, which may have therapeutic implications in nonalcoholic steatohepatitis, obesity, type 2 diabetes, and related metabolic disorders." (PMID 29295856, 2018). "Thus, it was possible that FGF21 failed to exert its expected effects on glucose homeostasis and lipid oxidation, which led some researchers to hypothesize that obesity was an FGF21-resistant state." (PMID 28466020, 2017). "Thus, the biological role of FGF21 in obesity and insulin resistance is still not fully explained and further understanding the regulation of FGF21 with the aim of modulating physiological levels maybe key in maximizing its therapeutic potential." (PMID 28256636, 2017). "Furthermore, these data indicate that obesity does not induce FGF21 resistance in NZO mice." (PMID 28770320, 2017). "However, the beneficial effects of FGF21 on obesity-induced insulin resistance in liver and muscle were not exhibited in adiponectin knockout mouse, suggesting that adiponectin is a downstream effector molecule of FGF21." (PMID 28025491, 2016). "However, mounting studies also support that plasma FGF21 levels are markedly increased in obesity, insulin-resistant, hypertriglyceridemia, hepatosteatosis and liver injury states, suggesting that FGF21 did not exert its beneficial effects on lipid and glucose homeostasis." (PMID 26914024, 2016). "However, no study has shown the direct involvement of FGF21 in obesity related CVD." (PMID 24498293, 2014). "The elevated FGF-21 levels in MASLD groups, regardless of obesity status, indicate its potential as a marker of metabolic stress in adolescents." (PMID 39910885, 2025).
Obesity (continued). "FGF-21 is significantly increased in PCOS patients, as reported by several studies, and this elevation occurs regardless of obesity." (PMID 39858445, 2025). "This is in line with the almost weight-neutral effects of long-acting FGF21 analogs, including efruxifermin and BOS-580, in individuals with obesity with or without type 2 diabetes." (PMID 41150667, 2025). "However, induction of FGF21 levels in adult obese mice, by inducible deletion of the mitochondrial fusion protein optic atrophy 1 (OPA1) in skeletal muscle, was able to reverse DIO, suggesting that induction of this pathway after the onset of obesity may still exert beneficial metabolic effects." (PMID 37818094, 2023). "Although activation of the ISR in BAT led to resistance to diet-induced obesity (DIO) in an ATF4-dependent manner, this phenomenon was independent of FGF21." (PMID 37819027, 2023). "Many studies have revealed no significant increase in levels of UCP1 and/or FGF21 (Fibroblast growth factor 21) in BAT, although the dose of n−3 PUFAs requisite for exerting an anti-obesity effect was increased threefold." (PMID 32595696, 2020). "Actually, despite of FGF21 reduction in type 1 diabetes and latent autoimmune diabetes in adults (LADA), circulating FGF21 levels were elevated in obesity, type 2 diabetes, dyslipidemia and non-alcoholic fatty liver disease (NAFLD)." (PMID 25850006, 2015). "However, melatonin did not protect against obesity, insulin resistance, and energy expenditure in HFD-fed FGF21−/− mice." (PMID 36207302, 2022). "Furthermore, FGF21 and GDF15 have been reported to be elevated in a range of non-mitochondrial disorders, including cancers, obesity, renal diseases, diabetes, and liver diseases." (PMID 35498801, 2022). "However, mechanisms independent of FGF21, but dependent on ATF4 induction, promote resistance to diet-induced obesity in OPA1 BAT KO mice." (PMID 33944779, 2021). "In addition, these results show that, in a state of increased weight (overweight and obesity), T2DM does not expressively alter the biological relationship between adiposity and circulating FGF-21." (PMID 30298107, 2018). "However, FGF-21 did not improve NAFLD, obesity or T2DM, possibly owing to FGF-21 resistance." (PMID 40465044, 2025). "Another possible explanation as to why FGF-21 levels increase after HCV eradication may lie in the concept of FGF-21 resistance, a condition already described, though not free of controversy, in murine models of obesity." (PMID 37999215, 2023).
Insulin resistance (415 papers, 2010 to 2026). Increased resistance towards insulin, that is, diminished effectiveness of insulin in reducing blood glucose levels. "In the present study, threshold levels of FGF-21, Metrnl, and sortilin were identified for the first time, associated with the presence of insulin resistance and dysglycemia." (PMID 40559404, 2025). "Metabolic biomarkers such as FGF21, TyG index, and adiponectin were closely linked to insulin resistance and hepatic steatosis, indicating their suitability for early diagnosis and high-risk population screening." (PMID 40951433, 2025). "Correlation analyses revealed that hepatic ChREBPβ expression was positively associated with insulin resistance and FGF21, suggesting coordinated regulation under metabolic stress." (PMID 41373582, 2025). "In this study, we found that in GDM, aggravated adipose tissue insulin resistance and inflammation are associated with impaired FGF21 signaling." (PMID 39599611, 2024). "This resistance, characterized by increased circulating FGF21 and decreased receptor expression, has been associated with a compensatory increase in adiponectin levels in obese individuals, those with insulin resistance, and heart failure patients." (PMID 39687000, 2024). "Genetic or pharmacologic inhibition of ASBT decreases blood glucose levels associated with decreased insulin resistance and increased hepatic FGF21 expression in mice." (PMID 39063026, 2024). "Consistently, mTORC1 is activated, and hepatic insulin resistance is exacerbated in FGF21-deficient mice." (PMID 36594101, 2023). "Serum FGF21 was determined by enzyme-linked immunosorbent assay (ELISA), in all groups, and correlated with biochemical parameters of glucose metabolism and insulin resistance (HbA1c, HOMA index, TG, and HDL cholesterol)." (PMID 37869250, 2023). "FGF19 and FGF21 have been shown to be associated with insulin resistance, which suggests their potential relevance as predictive factors for GDM development." (PMID 38139126, 2023). "FGF19 and FGF21 are thought to be associated with insulin resistance, an essential element in the pathogenesis of GDM." (PMID 38139126, 2023). "Chronic high levels of circulating FGF21 are considered as FGF21 resistant state, similar to insulin resistance, and is a risk factor for type 2 diabetes and cardiovascular diseases." (PMID 35192641, 2022). "In humans, increased levels of plasma FGF21 can predict metabolic syndrome and type 2 diabetes in healthy subjects, and are associated with insulin resistance, metabolic syndrome, type 2 diabetes, NAFLD and an increased risk of CVD." (PMID 35163521, 2022). "In our study, FGF21 correlated with waist circumference, triglycerides, total cholesterol, γ-GT, and the homeostatic model assessment of insulin resistance, which are identified as the main risk factors of NAFLD." (PMID 35663311, 2022). "In palmitic acid-induced HK-2 cells, alprostadil ameliorated renal tubular insulin resistance and restored autophagy via an autophagy-dependent fibroblast growth factor 21-associated pathway." (PMID 36091814, 2022). "FGF21 and adiponectin are described as insulin sensitizers, and a high leptin level is associated with insulin resistance." (PMID 35327418, 2022). "Accordingly, circulating FGF21 levels have been reported to positively associate with BMI, body fat, liver fat content, blood pressure, insulin resistance (IR) and atherogenic lipid profiles, as well as predict incident metabolic syndrome and T2DM." (PMID 36501091, 2022). "Transferring the FGF21 gene to healthy mice using adeno-associated viral vectors prevented age-related weight gain and insulin resistance and promoted healthy ageing." (PMID 35011721, 2022). "In particular, FGF21 has been shown to improve weight loss, lipid metabolism, and insulin resistance, and a phase 3 study of the application of an FGF21 analogue, pegbelfermin, in NAFLD treatment is ongoing." (PMID 35453652, 2022).